CTLA4 (cytotoxic T-lymphocyte associated protein 4)
Diseases named in the same sentence as CTLA4 in open-access papers (continued):
Sharing a sentence is not in itself a finding about the gene and the disease.
colorectal cancer (continued). "For example, a preclinical study of colorectal carcinoma found that the optimal timing for the anti-CTLA4 blockade is before RT, while for anti-OX40 agonists, the best time is after RT." (PMID 32983998, 2020). "The consensus molecular subtype I (CSM I) for colorectal carcinoma is characterized by a high expression of PD-1, CTLA-4, IDO1 and other immune checkpoints." (PMID 31960110, 2020). "Then, to determine the potential beneficial effects of lysates on immunotherapy in colorectal cancer, combined administration of lysates and anti-CTLA-4 IgG was started at day 51 and performed once every two days for the duration of this study." (PMID 31882868, 2019). "Immune checkpoint inhibitors, such as antibodies that block CTLA-4 and PD-1 signaling, are effective only in a fraction of colorectal cancers that show microsatellite instability (MSI)." (PMID 31775909, 2019). "Alternatively, in a mouse model of colorectal cancer, treatment with anti-CTLA-4 one week prior to treatment with RT, was shown to be superior to treatment with anti-CTLA-4 one week after the RT." (PMID 30360504, 2018). "Mice bearing CT26 colorectal carcinomas were responsive to single agent anti-CTLA4 treatment initiated closely following tumor implantation (p < 0.01)." (PMID 29725089, 2018). "An early study utilizing a CTLA-4 antagonist mAb, Tremelimumab, demonstrated the possibility of activity of immune checkpoint inhibitors in colorectal cancer, producing one response durable to 6 months." (PMID 28492495, 2017). "In a mouse model of KRAS-mutant colorectal cancer, anti-CTLA-4 profoundly increases the extent of T-cell activation and infiltration into tumors, and these effects were found to be only minimally impacted by MEK inhibition." (PMID 28807001, 2017). "Importantly, high abundance of GPR182+ PSCs correlated with poor prognosis and elevated expression of immune checkpoints (PD-L1 and CTLA-4) in colorectal cancer." (PMID 41918858, 2026). "Additionally, colorectal cancer cells have been shown to obtain other immune regulatory molecules such as CTLA4 through trogocytosis with infiltrating lymphocytes." (PMID 40440354, 2025). "In this study, we reported that 3 hub genes and transcriptional regulator factors could be regulated functional and specific gene in colorectal cancer by targeting miR-497 /CTLA-4 axis." (PMID 39905036, 2025). "In addition, increased expression of CTLA-4 has been established in colorectal cancer tissues compared to normal tissues." (PMID 41141615, 2025). "PD-1 blockade (pembrolizumab, nivolumab, sintilimab, toripalimab, camrelizumab, and others) and CTLA-4 blockade (ipilimumab and others) have been applied in immunotherapy for colorectal cancer, while the application of PD1 blockade is more widespread than CTLA-4 blockade." (PMID 40376001, 2025). "Our results warrant future clinical and mechanistic studies to determine whether dMMR/MSI GALNT7-Low colorectal cancers derive greater benefit from PD-1/PD-L1 blockade, alone or in combination with a CTLA-4, TIM-3, or LAG-3 inhibitor." (PMID 40824763, 2025). "Monoclonal antibodies targeting immune checkpoints such as programmed death-1 (PD-1)/programmed death-ligand 1 (PD-L1) and cytotoxic T lymphocyte-associated protein 4 (CTLA-4) have demonstrated remarkable efficacy, including in patients with colorectal cancer (CRC)." (PMID 40724985, 2025). "Importantly, a novel anti-CTLA-4 antibody called botensilimab is being investigated for its potential to treat refractory colorectal cancers, including those with microsatellite stability (MSS)." (PMID 41035646, 2025). "Among the immune dynamics explored, we observed a consistent expansion of regulatory T cells (Tregs) following PD-1 blockade, a finding that aligns with its limited efficacy as monotherapy in pMMR colorectal cancers and its enhanced activity when combined with CTLA-4 inhibitors." (PMID 41514641, 2025). "Clinical trials based on CTLA-4 inhibitors in the treatment of colorectal cancer." (PMID 41112277, 2025).
colorectal cancer (continued). "Their findings demonstrated that PD-L1 and CTLA-4 siRNA-loaded exosomes could suppress colorectal cancer progression and improve tumor immune responses." (PMID 39355533, 2024). "Therefore, the combination of sh-circQSOX1 and anti-CTLA-4 therapy is expected to provide a new direction for treating Treg cell-mediated immunotherapy resistance in colorectal cancer." (PMID 39759516, 2024). "It has been observed that CTLA-4 and PD-L1 expressions are high in colorectal cancer cells." (PMID 39355533, 2024). "Knockdown of circQSOX1 could effectively improve the sensitivity of colorectal cancer tumors to CTLA-4." (PMID 37781524, 2023). "A study of nivolumab monotherapy and nivolumab + ipilimumab (an anti-CTLA-4 antibody drug) combination therapy in patients with dMMR colorectal cancers (CheckMate-142 study) reported good outcomes with the ORRs of 31% and 55%, respectively, and the median PFSs was not reached in either group." (PMID 37599324, 2023). "Another study demonstrated the capacity of capecitabine, a chemotherapeutic agent, to downregulate CTLA4 expression on CRC (colorectal cancer) tissues, shedding light on its immunomodulatory capacity in addition to its previously known disruption of DNA synthesis." (PMID 37259163, 2023). "Indeed, CTLA-4, capecitabine, chemotherapy in colorectal cancer and immune checkpoint, immune checkpoint inhibitors and immunotherapy are crucial topics and should be given more attention in the future." (PMID 38125935, 2023). "To determine if an anti-IFNγ immunoPET tracer could identify intratumoral immune activity after ICI, we utilized BALB/c mice bearing subcutaneous CT26 colorectal cancer as a responsive model for combined ICI (anti-CTLA4 and anti-PD-1) therapy." (PMID 38130991, 2023). "Inhibition of PD-L1 and CTLA-4 is beneficial to the treatment of patients with colorectal cancer." (PMID 36132144, 2022). "Similarly, treatment of colorectal cancer-bearing mice with anti-CTLA-4 antibodies decreased Foxp3+/CD4+ Treg cells, but increased CD4+ T and CD8+ T cells and the expression levels of pro-inflammatory Th1/M1-related cytokines IFN-γ, IL-1α, IL-2, and IL-12." (PMID 35159059, 2022). "Importantly, in advanced stages of colorectal cancer, the levels of CTLA-4 mRNA in tumor tissues were shown to be higher." (PMID 36146549, 2022). "Therefore, combining CTLA-4 blockers with other drugs for colorectal cancer is a primary research direction." (PMID 35911673, 2022). "Furthermore, immunocheckpoint and cytotoxic T lymphocyte antigen-4 (CTLA-4) is an inhibitory immune checkpoint that can be expressed in tumor-infiltrating lymphocytes and colorectal cancer (CRC) cells." (PMID 35535032, 2022). "To investigate whether [177Lu]Lu-DUNP19 therapy could synergize with immune checkpoint inhibitors, we combined [177Lu]Lu-DUNP19 RIT with immune checkpoint blockade (anti-CTLA4 + anti-PD1) in the syngeneic MC38 colorectal cancer model (LRRC15- cancer cells, LRRC15+ stroma)." (PMID 41022704, 2025). "High ICOSL RNA was associated with colorectal cancer, not-high PD-L1, and with high CTLA-4." (PMID 40297627, 2025). "Using a preclinical model of colorectal cancer (cecum-based orthotopic transplantation), the authors observed that intravenous injections of miR-424 led to the downregulation of tumor-secreted vesicles, which improved response compared with combined anti-PD-1 and anti-CTLA-4 therapy." (PMID 38339019, 2024). "Similarly, CTLA-4 has been considered a marker for immunosurveillance in colorectal cancers." (PMID 39355533, 2024). "For example, combinatorial blockage of cytotoxic T lymphocyte associated protein 4 (CTLA-4) and programmed cell death protein 1 (PD-1) checkpoint receptors led to increased progression-free survival (PFS) and overall survival (OS) rates in MSI colorectal cancer patients." (PMID 39242638, 2024). "However, CTLA-4 blockers alone are ineffective in treating colorectal cancer." (PMID 35911673, 2022).
colorectal cancer (continued). "There is also growing evidence for increased TIM3, CTLA‐4, and PD‐1 expression in MSI compared to MSS colorectal cancers." (PMID 40181205, 2025). "However, certain malignancies, such as gastro-esophageal and colorectal cancer, fail to respond to immune checkpoint inhibitor (ICI) therapy such as KeytrudaTM (anti-programmed cell death protein 1, anti-PD-1) or YervoyTM (anti-cytotoxic T-lymphocyte-associated protein 4, anti-CTLA-4)." (PMID 41035646, 2025). "In colorectal cancer, m6A-modified circular RNA QSOX1 induces regulatory T cells, contributing to anti-CTLA4 resistance." (PMID 41390674, 2025). "In this study, TAK-981 improved the survival of mice in models of colorectal cancer, enhancing the response of anti-PD1 or anti-CTLA4 antibodies." (PMID 40804185, 2025). "Our study also found a positive correlation between VISTA, CTLA4, PDL1, PD1checkpoints, and TILs, which was confirmed by a recent study in HGSOC in colorectal cancer, TNBC, and hepatocellular carcinoma." (PMID 38634058, 2024). "Recent studies have shown exceptional responses to neoadjuvant immunotherapy with botensilimab (anti-CTLA-4) and balstilimab (anti-PD-1) for pMMR/MSS colorectal cancer, suggesting another approach to improve tumor regression and restore the TiME." (PMID 39409972, 2024). "In colorectal cancer, EPAS1 expression was significantly correlated with the expression of well‐known T cell checkpoints including PD‐1, PD‐L1 and CTLA‐4." (PMID 37994607, 2024). "Colorectal cancer also demonstrated comparable results, as anti-VISTA therapy proved effective in conquering resistance to anti-PD-1/CTLA-4 treatment." (PMID 38357542, 2024). "Blood samples of three colorectal cancer patients with dMMR/MSI-H have been used to assess PD-1 and CTLA-4 combined treatment response with ctDNA, CEA, and CA19-9." (PMID 37635168, 2023). "The results showed that in colorectal cancer, the high expression of NOLC1 was closely related to multiple immune checkpoints, such as LAG3, CTLA-4, and PDCD1LG2, leading to immune tolerance or escape of tumor cells." (PMID 37670166, 2023). "Further studies are needed to establish the mechanisms of CTLA-4 and LAG3 in patients with colorectal cancer." (PMID 35434132, 2022). "A subset of patients also responded to immunotherapy that targets PD-1 or CTLA-4 checkpoints, suggesting the critical role of the tumor immune microenvironment (TME) in the progression and treatment of colorectal cancer." (PMID 36172359, 2022). "Loss of ARID1A was found to have a significant correlation with the expression of IFN-γ and checkpoint genes (including PD-L1, CTLA4, and PDCD1) in microsatellite-stable colorectal cancer." (PMID 35198440, 2022). "A total of 30 mice were divided into three treatment groups in an experiment using the mouse colorectal cancer model CT26: untreated, anti-PD-1 antibody monotherapy, or anti-PD-1 and anti-CTLA-4 antibody combination (DICB)." (PMID 36275766, 2022). "In particular, in the colorectal cancer model CT26, anti-CTLA-4 mAb, injected seven days before RT, induced better tumor responses leading to long term tumor control, compared with anti-CTLA-4 given one or five days post-irradiation." (PMID 33530329, 2021). "To study the response patterns to ICB treatment, we first used the mouse CT26 colorectal cancer cell line model, which shows moderate response to anti-PD1 or anti-CTLA4 treatment with remarkable heterogeneity." (PMID 33059736, 2020). "To characterize the impact of selumetinib on the immuno-modulatory effects of anti-CTLA-4, we utilized the subcutaneous CT26 mouse colorectal cancer model." (PMID 28807001, 2017). "As PD-1 and CTLA-4 have demonstrated synergy in multiple tumor types, recent efforts to explore these combinations have also been pursued in MSS colorectal cancer." (PMID 28492495, 2017). "Immunobased therapies, including those targeting CTLA4 and PD1, are also the focus of clinical trials for colorectal cancer." (PMID 27413734, 2016).
colorectal cancer (continued). "MoST-CIRCUIT is the first trial to investigate immunotherapy using combined anti-PD-1/CTLA-4 checkpoint blockade in patients with advanced dMMR/MSI-H non-colorectal cancers." (PMID 41231502, 2026). "M6A-modified circQSOX1 promoted colorectal cancer tumorigenesis by promoting PGAM1 expression by sponging miR-326 and miR-330-5p and further facilitated colorectal immune escape by activating glycolysis and inactivating anti-CTLA-4 therapeutic response." (PMID 38778089, 2024). "In the Canadian Cancer Trials Group CO.26 study, MSS colorectal cancer patients with elevated plasma TMB levels (≥28 muts/Mb) showed predictable responses to the combination therapy of the anti-PD-L1 drug durvalumab and the anti-CTLA4 drug tremelimumab." (PMID 38613793, 2024). "Similar results were found in colorectal cancer, for which anti-VISTA treatment could overcome resistance to anti-PD-1/CTLA-4 treatment." (PMID 37190254, 2023). "Furthermore, a positive correlation was observed between the expression of CDKN2A and various immune checkpoint genes in colorectal cancer, namely PDCD1, CTLA-4, and CD274." (PMID 37950153, 2023). "In this study, we loaded colorectal cancer (CRC) cell lysate on DCs and inhibited the expression of CTLA-4 by small interfering RNA (siRNA) in them to investigate the DCs’ functional and phenotypical features, and T-cell mediated responses following DC/T cell co-culture." (PMID 35979362, 2022). "In a colorectal cancer mouse model, the combination of RT and anti-CTLA4+PD1 increased tumour shrinkage in non-irradiated liver metastases in comparison to RT-IgG or RT+anti-CTLA4." (PMID 36476325, 2022). "The combination of PD-1/PD-L1 and CTLA-4-blocking antibodies may have a controllable safety profile and inspiring antitumor activity in MSS/pMMR colorectal cancer patients." (PMID 36275766, 2022). "Intraperitoneal injection of a localized low-dose anti-CTLA-4 mAb has controlled the growth of colorectal cancer in mice and was not inferior to the administration of a systemic high-dose treatment." (PMID 34966384, 2021). "This randomized phase 2 study suggests that combined PD-L1 and CTLA-4 blockade with durvalumab and tremelimumab may prolong OS in patients with heavily pretreated MSS colorectal cancer." (PMID 32379280, 2020). "Collectively, this data suggests no generalizable activity of PD-1 monotherapy for MSS colorectal cancer and only very limited activity with PD-1 and CTLA-4 combination therapy." (PMID 28492495, 2017). "In TILs from colorectal cancer patients, CD8+ T cells in close contact with Tregs have about 2-fold higher PD-1 expression levels compared to CD8+ T cells distant from Tregs, indicating that Treg CTLA4 signaling plays a crucial role in driving T cell exhaustion." (PMID 41415289, 2025). "High ICOS (⩾75 percentile RNA rank) was present in 14% of 514 cancers and independently associated with high PD-1 (p = 0.025), PD-L1 (p < 0.0001), and CTLA-4 RNA expression (p < 0.0001) and with patients not having colorectal cancer (p = 0.0009; multivariate analysis)." (PMID 40297627, 2025). "Although the anti-CTLA-4xSIRPα construct has less binding affinity toward CTLA-4, it was more effective than anti-CTLA-4 plus anti-CD47 combination treatment in depleting highly immunosuppressive ICOShigh intra-tumoral Tregs and reducing tumor burden in colorectal cancer mouse models." (PMID 35326731, 2022). "Combined with tumor stage, TMB, CTLA4, and PD-L1 expression, MSI status, and TME phenotype, CuproptosisScore can serve as an effective predictive schedule for prognosis and contribute to performing patient stratification for the determination of immunotherapy regimen in colorectal cancer patients." (PMID 36248908, 2022). "CTLA-4 and PD-1/L1 may yet prove beneficial in some subsets of MSS colorectal cancers." (PMID 28492495, 2017).
colorectal cancer (continued). "Furthermore, the relationship between SIGLEC15,TIGIT,LAG3,CTLA4, PDCD1LG2 immune checkpoints and Mapk14 was only verified by correlation analysis, and we need to further explore the mechanism of Mapk14 expression in colorectal cancer in vitro and vivo experiments, such as single cell RNA sequencing." (PMID 35141222, 2022). "In MM mouse models, depletion of FAPα+ macrophages significantly boosted the efficacy of anti-PD-1/PD-L1 antibody therapy but not anti-CTLA-4 therapy; this combinatorial strategy also exerted enhanced anti-tumor effects in EL4 lymphoma and CT26 colorectal carcinoma models." (PMID 41614659, 2026).